OR52E4 (olfactory receptor family 52 subfamily E member 4)
Description:
Odorant receptor.
Synonyms: OR11-55
Tractability: Antibody: UniProt places it where antibodies can reach, with medium confidence; UniProt predicts a signal peptide or a membrane-spanning region; its Gene Ontology location is reachable by antibodies, with medium confidence.
Gene: Protein-coding gene on chromosome 11 (5,880,629 to 5,887,079, forward strand). Ensembl gene ENSG00000180974.
Subcellular location: Cell membrane
Pathways (Reactome):
Sensory Perception: Expression and translocation of olfactory receptors
Gene Ontology:
Molecular function: olfactory receptor activity; G protein-coupled receptor activity
Biological process: detection of chemical stimulus involved in sensory perception of smell; G protein-coupled receptor signaling pathway; nervous system process
Cellular component: plasma membrane; membrane
Genetic constraint (gnomAD): Loss-of-function variants: 6 observed, 3.19 expected, observed/expected ratio (o/e) 1.88, 90% interval 0.86 to 1.96. That is too few expected variants to judge how well the gene tolerates losing a copy. Missense variants: 443 observed, 403.34 expected, observed/expected ratio (o/e) 1.1, 90% interval 1.01 to 1.19. Synonymous variants: 169 observed, 144.36 expected, observed/expected ratio (o/e) 1.17, 90% interval 1.03 to 1.33.
Homologues: Orthologues: chimpanzee OR52E4 (99% identical), macaque OR52E4 (92% identical), dog OR52E4B (88% identical), rat Or52e4 (87% identical), mouse Or52e4 (86% identical), tropical clawed frog or52m1 (47% identical). Paralogues in human: OR52E8 (69% identical), OR52E2 (68% identical), OR52E5 (67% identical), OR52E6 (67% identical), OR52E1 (58% identical), OR52J3 (57% identical), OR52H1 (55% identical), OR52B2 (54% identical), OR52D1 (53% identical), OR52N4 (52% identical), OR52N2 (51% identical), OR52N5 (51% identical), and 39 more.